MTOR (mechanistic target of rapamycin kinase)
Diseases named in the same sentence as MTOR in open-access papers (continued):
Sharing a sentence is not in itself a finding about the gene and the disease.
sarcopenia (continued). "The suppression of the AKT/mTOR signaling pathway, a major anabolic pathway that controls muscle mass, is considered a critical contributor to the progression of sarcopenia." (PMID 40943208, 2025). "An anabolic resistance response in the presence of activation of the mTOR signalling pathway can characterise sarcopenia." (PMID 40937507, 2025). "Both RT and aerobic training are beneficial for remedying sarcopenia by modulating the AKT/mTOR, AKT/FoxO3a, and AMPK signalling pathways, as well as by enhancing BCAA uptake and absorption." (PMID 39169398, 2024). "We found that GABA inhibits sarcopenia by regulating muscle protein degradation through the activation of Akt/mTOR/FoxO3a signalling pathways." (PMID 39513373, 2024). "Myonectin acts via the Akt/mTOR system, a nutrient-responsive anabolic pathway, protecting against sarcopenia." (PMID 38999757, 2024). "MTOR plays a crucial role in controlling muscle anabolic and catabolic pathways, making it a potential therapeutic target for combating sarcopenia." (PMID 39519004, 2024). "The signaling pathways involving mTOR and FoxO transcription factors play important roles in the development of sarcopenia and muscle atrophy." (PMID 39101140, 2024). "Inhibition of protein synthesis in patients with diabetic sarcopenia is mediated by inhibition of the IGF1-PI3K-Akt-mTOR pathway." (PMID 38594634, 2024). "Under normal conditions, the nutrition from GB powder can be used for triglyceride synthesis in WAT, whereas in sarcopenia, it can be used for muscle synthesis by activating the Akt/mTOR/S6K signaling pathway, which is upstream of MyHC." (PMID 37324877, 2023). "Hyperammonaemia has a pleiotropic effect on muscle cells as it inhibits the mTOR complex (mTORC1), resulting in autophagy, blunted protein synthesis and sarcopenia." (PMID 35052859, 2022). "Conversely, the expression of the IGF-1 receptor increases with aging, possibly as a compensatory response to lower IGF-1 levels, leaving open the question as to why mTOR activation is enhanced in sarcopenia." (PMID 36430301, 2022). "RE can also induce autophagy, which is closely related to sarcopenia, by regulating Akt/mechanistic target of rapamycin (mTOR) and Akt/FOXO3a signaling pathways, as well as AMPK-mediated mitochondrial quality control." (PMID 36035464, 2022). "Nutritional supplementation plays an important role in the prevention of ICUAW and the development of sarcopenia, especially protein sufficiency, in an attempt to influence the link between proteosynthetic mTOR and proteolytic UPS." (PMID 35955530, 2022). "Such a role has been described also in patients with liver cirrhosis, in whom alterations in the mTOR pathway and autophagy are indicated as mediators of sarcopenia." (PMID 36430301, 2022). "P38/MAPK, JAK/STAT, Notch, mTOR, and other signaling pathways are aberrantly expressed within MuSCs during aging, and Stat3 has been identified to increase activity in sarcopenia." (PMID 36035464, 2022). "Chronic inflammation promotes protein catabolism in muscle cells and the development of sarcopenia, probably due to the inhibition of Akt/mTOR pathway and to the induction of ubiquitin-proteasome system (UPS)." (PMID 35052859, 2022). "In muscle, the mammalian target of rapamycin, known as mTOR, is the central controller of protein synthesis, and its inhibition is a crucial mechanism for GC excess-related sarcopenia." (PMID 35054858, 2022). "Intervention strategies targeting mTOR in sarcopenia (e.g., supplementation of plant extracts, hormones, inorganic ions, calorie restriction, and exercise) have also been discussed." (PMID 36430301, 2022). "The mammalian target of rapamycin (mTOR) is a key regulator of muscle anabolic and catabolic pathways and, hence, a promising target for interventions against sarcopenia." (PMID 36430301, 2022).
sarcopenia (continued). "We would like to concentrate the effect of AM on Akt/mTOR pathway first before resolving the issue of sarcopenia, since the level of Akt/mTOR phosphorylation is considered to be a good predictor of increased muscle hypertrophy." (PMID 35458232, 2022). "Here, we provide an overview of mTOR signaling in skeletal muscle, with a special focus on the role played by mTOR in the development of sarcopenia." (PMID 36430301, 2022). "Dysregulation of PI3K/Akt/mTOR leads to a decrease in proteosynthesis and contributes to the development of muscle atrophy and sarcopenia." (PMID 35955530, 2022). "Based on the results of immunohistochemistry and increased phosphorylation of Akt and mTOR, we suggest that the addition of maca appears to be effective in the treatment of sarcopenia." (PMID 35743270, 2022). "Previous reports indicated that the muscle damaged in sarcopenia was importantly related to the downregulation of p70S6K/mTOR/4EBP1 pathway." (PMID 33804803, 2021). "Ironically, although anabolic resistance presents an issue in sarcopenia, constitutive activation of the Akt/mTOR pathway promotes sarcopenia." (PMID 34445751, 2021). "In contrast, other findings revealed that the mTOR inhibitor rapamycin surprisingly ameliorates muscle function in a number of muscular dystrophies, and overactivation of mTOR leads to sarcopenia." (PMID 34680438, 2021). "Compared with the control group HF + sarcopenia group had decreased p-mTOR/mTOR (P < 0.05) and p-Akt/Akt (P < 0.05), indicating that HF + sarcopenia group had reduced protein synthesis." (PMID 35126176, 2021). "To note, four of the human pathways (MAPK, FoxO, TGFβ and mTOR signalling pathways) were indicated by bioinformatic analysis were previously indicated involved in sarcopenia." (PMID 34289870, 2021). "Exercise is important in the prevention of sarcopenia because it is involved in the activation of the mammalian target of the rapamycin (mTOR) signaling pathway in skeletal muscle." (PMID 32961753, 2020). "Mechanistically, the modulation of the Akt/mTOR, Akt/FOXO3a, and AMPK signal pathways are implicated in the mitigation of sarcopenia upon exercise interventions." (PMID 33224037, 2020). "The association of anabolic properties targeting mTOR and anti-proteolytic properties, makes supplementation with HMB of potential efficacy for the treatment of sarcopenia after liver transplantation." (PMID 31546969, 2019). "We also detected transcriptional signatures of altered mTOR signaling, translation, and protein synthesis in human sarcopenia, consistent with the role of anabolic resistance in the decline of muscle mass and strength during aging." (PMID 31862890, 2019). "Previous reports have suggested an involvement of reduced activation of the phosphatidylinositol 3-kinase-Akt-mammalian target of rapamycin (mTOR) pathway, which promotes protein synthesis, in the development of sarcopenia." (PMID 29912922, 2018). "A similar interaction between sarcopenia and toxicity was observed in a retrospective analysis of 112 mRCC patients treated with mTOR inhibitors, immunotherapy, VEGF inhibitors, Tyrosine Kinase Inhibitors (TKIs), and best supportive care." (PMID 28326276, 2016). "In conclusion, both sarcopenia and muscular dystrophy exhibit the marked defect of autophagy-dependent signaling possibly the latter due to hyperactivation of Akt/mTOR/p70S6K pathway." (PMID 25221510, 2014). "One important example of the importance of mTOR in the metabolic regulation of muscle mass can be observed during the process of age-related muscle wasting and weakness (sarcopenia)." (PMID 24567722, 2014). "In contrast, the adaptation of mTOR-dependent signaling seems to differ between sarcopenia and muscular dystrophy to some extent." (PMID 25221510, 2014). "However, current researches on exercise interventions for sarcopenia still lacks investigation into skeletal muscle mTOR signaling." (PMID 40950953, 2025).
sarcopenia (continued). "Blocking mTOR signaling might extend life span and prevent the onset of age‐related diseases in mammals (e.g., sarcopenia), suggesting that mTOR inhibitors exert beneficial effects on human longevity." (PMID 39764565, 2025). "Activation of the PI3K/AKT/mTOR pathway promotes muscle growth, whereas T therapy may suppress this pathway, impairing muscle protein synthesis and exacerbating sarcopenia." (PMID 40109345, 2025). "These components contribute to whey protein’s effectiveness in combating malnutrition and sarcopenia by promoting muscle protein synthesis, primarily through leucine’s activation of the mammalian target of rapamycin (mTOR) pathway, a central regulator of muscle growth and repair." (PMID 40806373, 2025). "Thus, investigation on the role of mTOR in muscle mitochondrial biogenesis is essential for adjusting exercise and nutritional methods to maximize aerobic capacity for sarcopenia patients." (PMID 40950953, 2025). "Importantly, the mTOR pathway—an atypical threonine/lysine kinase signaling axis—was markedly suppressed in individuals with sarcopenia." (PMID 41568005, 2025). "Therefore, the activation of the IGF‐1/Akt/mTOR pathway in muscles plays an important role in ameliorating sarcopenia by promoting muscle protein synthesis." (PMID 39513373, 2024). "This is the first study reporting that SCFAs cocktail mainly produced by beneficial gut bacteria could attenuate age‐related sarcopenia through the mTOR signalling pathways." (PMID 39482890, 2024). "Thus, proper activation of the IGF‐1/Akt/mTOR pathway plays an important role in preventing sarcopenia and maintaining muscle health." (PMID 39513373, 2024). "In addition, SELENOW KO down-regulated the phosphorylation of mTOR at S2248 in two sarcopenia models." (PMID 39303039, 2024). "Therefore, activation of the Akt/mTOR pathway in muscle should ameliorate sarcopenia by promoting muscle protein synthesis." (PMID 37759480, 2023). "Sarcopenia is characterized by anabolic resistance even in the setting of chronic mTOR activation." (PMID 36430301, 2022). "Here, we provide an overview of the role of mTOR signaling in muscle protein metabolism and its implications in sarcopenia, as well as a description of current strategies being tested that harness this signaling pathway to manage sarcopenia." (PMID 36430301, 2022). "Moreover, the activation of inflammatory pathways, including mammalian target of rapamycin (mTOR) and nuclear factor erythroid-related factor 2 (Nrf-2) signalling, appears to be involved in the pathophysiology of sarcopenia and frailty." (PMID 34835952, 2021). "However, mice with heart failure and sarcopenia have significantly protein synthesis due to reduced p-Akt/Akt and p-mTOR/mTOR." (PMID 35126176, 2021). "MyoD is activated by mTOR (mammalian target of rapamycin), which controls the anabolic and catabolic signaling of skeletal muscle mass, resulting in the modulation of muscle hypertrophy and sarcopenia." (PMID 32316601, 2020). "Therefore, exercise-induced autophagy is beneficial for remedying sarcopenia by modulating Akt/mTOR and Akt/FoxO3a signal pathways and AMPK-mediated mitochondrial quality control, and resistance exercise exhibits the best interventional efficiency." (PMID 33224037, 2020). "After LT, prolonged bedrest, a hypoactive lifestyle, steroid therapy and the use of anti-rejection drugs, such as inhibitors of mTOR (Sirolimus and Everolimus), may affect recovery of muscle mass and even worsen sarcopenia." (PMID 31546969, 2019). "Because mTOR signaling is important for muscle hypertrophy, dysregulated mTOR signaling might play a role in sarcopenia development." (PMID 28738022, 2017). "Given the hyperactive state of mTOR signaling in obese skeletal muscle, normalizing mTOR signaling (to levels observed in lean mice) may be one avenue of limiting the resultant sarcopenia." (PMID 21386136, 2011).
sarcopenia (continued). "Moreover, while pathways such as IGF-1/Akt/mTOR, myostatin signaling, and inflammatory cascades have been characterized, controversies persist regarding the relative weight of each in different conditions (e.g., sarcopenia vs. cachexia)." (PMID 41220691, 2025). "Adequate dietary protein is required to activate the mTOR pathway and stimulate MPS, which occurs 2–5 h postprandially; however, MPS is decreased in older populations due to decreased activation of mTOR by ingested protein, leading to an increased risk of sarcopenia." (PMID 40806046, 2025). "Thus, resistance training combined with endurance training may be suitable for older adults because endurance training-induced AMPK activation inhibits the hyperactivation of mTOR, benefiting the mitochondrial biogenesis besides treatment of sarcopenia." (PMID 40950953, 2025). "Therefore, PI3K/AKT/mTOR pathway regulation may be a potential target for the treatment of sarcopenia." (PMID 39962589, 2025). "Therefore, the activation of AKT/mTOR might be attributed to SCFAs‐induced changes of IGF status in sarcopenia." (PMID 39482890, 2024). "Loss of muscle mass in sarcopenia patients is associated with an imbalance between muscle protein synthesis and catabolism, and HMB may increase muscle protein synthesis by activating the mammalian target of rapamycin (mTOR) pathway." (PMID 39360288, 2024). "Our findings revealed that AKT1 and MTOR are the crucial targets by which the active ingredients of Citri Reticulatae Pericarpium, particularly Sitosterol and Hesperetin, may act to alleviate sarcopenia through the PI3K-AKT signaling pathway." (PMID 39519004, 2024). "However, the role of the mTOR pathway in sarcopenia remains controversial." (PMID 37237929, 2023). "Moreover, BCAAs supplementation appears to improve lifespan, mitochondrial biogenesis (via SIRT1) and protein synthesis (via mTOR) in middle-aged mice, and to provide benefits for muscle mass, strength and protein synthesis rates in older subjects with pre-sarcopenia or sarcopenia." (PMID 36678201, 2023). "Furthermore, the impairment of the mTOR pathway has been observed in patients with sarcopenia." (PMID 37237929, 2023). "Hence, it indicated that WPPs might attenuate sarcopenia in vivo through two distinct mechanisms: by activation of Akt/mTOR signaling pathway and by reduction of inflammation levels and oxidative stress associated with aging." (PMID 36159451, 2022). "One of the diverse mechanisms known to contribute to the onset of sarcopenia is the slight but persistent increase in inflammatory mediators such as IL-1β, IL-6, and TNF-α that simultaneously impact muscle metabolism, causing wasting and loss via the mTOR pathway." (PMID 35954203, 2022). "Thus, gaining control of these initial signals and processes in obese, insulin resistant, and/or aging skeletal muscle with mTOR antagonists (e.g. rapamycin, metformin), may be beneficial to limiting sarcopenia and sarcopenia-related dysfunction." (PMID 21386136, 2011). "The PI3K/Akt and mTOR/P70S6K/4EBP1 signaling pathways play a crucial role in regulating muscle protein synthesis, a process that becomes disrupted in obese sarcopenia." (PMID 40871670, 2025). "Especially in the elderly, studies have revealed a strong correlation between sarcopenia and disuse muscle atrophy, with both sharing highly consistent molecular mechanisms, each relying on the PI3K/Akt/mTOR signaling pathway as a core regulatory mechanism." (PMID 40792295, 2025). "Emerging therapeutic strategies targeting the mTOR pathway, NAD+ metabolism, and senescence-related processes offer promise in mitigating sarcopenia’s progression." (PMID 39861412, 2025). "Of note, decorin alleviated skeletal muscle fibrosis and atrophy in D‐gal–induced aged mice and NOR‐10 cells by activating the ITGB1/Akt/mTOR signalling pathway, which suggests that decorin supplementation may be a potent therapeutic strategy to combat age‐associated sarcopenia." (PMID 41350105, 2025).
sarcopenia (continued). "Overall, impairment in anabolic signaling in sarcopenia, as evidenced by suppressed IGF‐1/AKT/mTOR pathway." (PMID 39764565, 2025). "In sarcopenia, increased ROS/RNS can prevent the phosphorylation of AKT kinase, mTOR, and the downstream mTOR targets p70S6K and E4E-BP1, thus impairing the ability of muscle cells to adapt to exercise." (PMID 40869107, 2025). "Specifically, elevated ROS such as hydrogen peroxide (H2O2) can suppress phosphorylation of mTOR, AKT, and other downstream signaling molecules, leading to muscle atrophy or sarcopenia due to inhibited protein synthesis." (PMID 41228405, 2025). "In sarcopenia, the PI3K/AKT/mTOR pathway activity is usually decreased, leading to decreased muscle satellite cell proliferation, differentiation, and protein synthesis, resulting in decreased muscle mass and function." (PMID 39962589, 2025). "These inflammatory factors promote muscle protein degradation by influencing mTOR and FOXO signaling pathways, leading to sarcopenia." (PMID 39101140, 2024). "In C2C12 cells mimicking sarcopenia, Olg combined with BCAA supplementation enhanced mTOR/p70S6K activity more than BCAA alone." (PMID 39519101, 2024). "Sarcopenia is closely related to major signaling pathways, including phosphatidylinositol 3-kinase (PI3K), protein kinase B (PKB)/AKT, mammalian target of rapamycin (mTOR), and ubiquitin-proteasome system (UPS)." (PMID 38540908, 2024). "Our findings suggest that the active ingredients of Citri Reticulatae Pericarpium, particularly Sitosterol and Hesperetin, have the potential to improve sarcopenia by interacting with AKT1 and MTOR proteins through the PI3K-AKT signaling pathway." (PMID 39519004, 2024). "In people with sarcopenia, exercise increases IGF-1/PI3K/AKT levels and subsequent mTOR activation to induce protein synthesis, while simultaneously suppressing FOXO signaling." (PMID 35250869, 2022). "The analysis of molecular pathways of IBD-related sarcopenia assessed by using immunohistochemistry showed a down-expression of IGF1-R and Phospho-mTOR, markers of muscle growth, and an over-expression of Murf-1 and Myostatin, considered markers of sarcopenia." (PMID 34326845, 2021). "Chemotherapy, which is used for cancer treatment, is also suggested to induce sarcopenia by decreasing protein synthesis by expressing molecules (such as Ras, Raf, MEK, and ER) and decreasing proliferation of muscle-cell by expressing mTOR." (PMID 31681607, 2019). "Several positive and negative regulators (mTOR, SRF, atrogin-1, p62, and myostatin) have been proposed to enhance protein degradation or transcription of muscle-specific genes during both sarcopenia and muscular dystrophy." (PMID 25221510, 2014). "Losartan, an ARB, has shown promising pre-clinical results in the treatment of disuse atrophy and impaired regeneration in the context of sarcopenia through the modulation of the TGF-β and Akt/mTOR pathways." (PMID 22184279, 2011). "Both vitamins are involved in pathways relevant to sarcopenia pathophysiology, including Nuclear factor-κB (NF-κB) signaling, Nrf2 antioxidant responses, and protein kinase B (AKT)/ mechanistic target of rapamycin (mTOR)-mediated protein turnover." (PMID 40867810, 2025). "For instance, IL‐25 ameliorates sarcopenia by promoting M2 macrophage polarization, which enhances satellite cell function and muscle regeneration through the sonic hedgehog/AKT (protein kinase B, PKB)/mTOR (mechanistic target of rapamycin) signaling pathway." (PMID 41357670, 2025). "Additionally, the role of advanced interventions, such as mTOR inhibitors, AMPK activators, and anti-inflammatory therapies, in modulating sarcopenia within cardiovascular populations remains underexplored." (PMID 39861412, 2025).